LDAH (lipid droplet associated hydrolase)
Description:
Probable serine lipid hydrolase associated with lipid droplets (By similarity). Has low cholesterol esterase activity (By similarity). Appears to lack triglyceride lipase activity (By similarity). Involved in cholesterol and triglyceride homeostasis; has opposing effects, stimulating cellular triglyceride accumulation and cellular cholesterol release. Acts antagonistically with PNPLA2/ATGL in regulation of cellular lipid stores. May regulate triglyceride accumulation indirectly through stimulation of PNPLA2/ATGL ubiquitination and proteasomal degradation. Promotes microtubule-dependent lipid droplet fusion. Highly expressed in macrophage-rich areas in atherosclerotic lesions, suggesting that it could promote cholesterol ester turnover in macrophages (By similarity).
Synonyms: hLDAH; C2orf43; FLJ21820
Tractability: PROTAC: ubiquitination databases record sites on it; its protein half-life has been measured.
Gene: Protein-coding gene on chromosome 2 (20,684,014 to 20,823,130, reverse strand). Ensembl gene ENSG00000118961.
Subcellular location: Lipid droplet; Endoplasmic reticulum
Gene Ontology:
Molecular function: sterol ester esterase activity; lipase activity
Biological process: cholesterol homeostasis; intracellular triglyceride homeostasis; lipid droplet fusion; lipid droplet organization; lipid storage
Cellular component: endoplasmic reticulum; lipid droplet
Genetic constraint (gnomAD): Loss-of-function variants: 27 observed, 31.82 expected, observed/expected ratio (o/e) 0.85, 90% interval 0.62 to 1.17. The upper end of that interval is the gene's LOEUF score, 1.17, which puts it in group 5 of 6, group 1 being the genes least tolerant of losing a copy. Missense variants: 338 observed, 403.01 expected, observed/expected ratio (o/e) 0.84, 90% interval 0.77 to 0.92. Synonymous variants: 116 observed, 139.42 expected, observed/expected ratio (o/e) 0.83, 90% interval 0.71 to 0.97.
Homologues: Orthologues: chimpanzee LDAH (99% identical), macaque LDAH (97% identical), dog LDAH (81% identical), pig LDAH (78% identical), guinea pig LDAH (71% identical), rabbit LDAH (68% identical), mouse Ldah (66% identical), rat Ldah (66% identical), tropical clawed frog ldah (47% identical), zebrafish ldah (44% identical), Caenorhabditis elegans F26A3.1 (25% identical), Caenorhabditis elegans F11C1.4 (22% identical), and 1 more.
Diseases named in the same sentence as LDAH in open-access papers:
LDAH is named in the same sentence as 15 diseases in open-access papers, as found by Europe PMC text mining. Sharing a sentence is not in itself a finding about the gene and the disease. The quoted sentences say what the papers report.
prostate carcinoma (3 papers, 2011 to 2018). A carcinoma that arises from epithelial cells of the prostate gland. "Additionally, the top SNP identified at 2p24.1 is in LDAH (previously known as C2orf43); SNPs in LDAH have also been associated with prostate cancer risk." (PMID 29659830, 2018).
atherosclerosis (1 paper, 2024). A disease characterized by the build-up of fatty material and calcium deposition in the arterial wall resulting in partial or complete occlusion of the arterial lumen. "Thus, we investigated how loss of LDAH affects atherosclerosis in mice challenged with a western diet (WD)." (PMID 39095402, 2024). "Atherosclerosis studies performed on mice with their bone marrows reconstituted with LDAH-deficient cells and studies under LDAH overexpression driven by a myeloid promoter suggest that LDAH expression in macrophage/foam cells is sufficient to induce these favorable effects." (PMID 39095402, 2024). "Using knockout and transgenic mice of both sexes, here we show that LDAH inhibits atherosclerosis development and promotes stable lesion architectures." (PMID 39095402, 2024). "We show that LDAH protects against atherosclerosis and promotes more benign plaque phenotypes, characterized by increased deposition of fibrillar collagen and reduced areas of necrosis." (PMID 39095402, 2024). "However, atherosclerosis development was significantly reduced in LdahTg/0Apoe−/− mice, both in male and female mice, indicating that LDAH is an atheroprotective player." (PMID 39095402, 2024).
prostate tumors (1 paper, 2018). "Rs13385191, which is suggested to be a cis-acting expressed quantitative locus (eQTL) that down-regulates the expression of LDAH, a gene that is frequently down-regulated in PCa and is even further reduced in metastatic prostate tumors as compared to primary prostate tumors." (PMID 29560112, 2018).
cancer (3 papers, 2023 to 2025). A tumor composed of atypical neoplastic, often pleomorphic cells that invade other tissues. "In total, 31 genes were overlapped in both datasets and 12 genes (i.e., CNBP, HDAC2, LDAH, RPL6 and EIF4G2) were annotated in Cancer Gene Census or CancerMine38,39." (PMID 36681772, 2023).
tumor (2 papers, 2022 to 2024). "Notably, LDAH was found upregulated in tumor tissue of PDA patients, leading to a connection between our observation in peripheral blood and the tumor." (PMID 39176093, 2024). "Most commonly, lncRNAs sponge to corresponding miRNA and mRNA that target critical metabolic enzymes, such as PKM2, LDAH, HK2, and glucose transporter GLUT1, to modulate the expression of numerous oncogenes and tumor-suppression genes." (PMID 36072431, 2022).
LDAH also shares sentences with these, for which no sentence is quoted: coronary heart disease (1 paper); COVID-19 (1); diabetes (1); kidney damage (1); leprosy (1); lung carcinoma (1); metastatic disease (1); Obesity (1); pancreatic cancer (1); sensorineural hearing loss (1).